STING1 (stimulator of interferon response cGAMP interactor 1)
Description:
Facilitator of innate immune signaling that acts as a sensor of cytosolic DNA from bacteria and viruses and promotes the production of type I interferon (IFN-alpha and IFN-beta). Innate immune response is triggered in response to non-CpG double-stranded DNA from viruses and bacteria delivered to the cytoplasm. Acts by binding cyclic dinucleotides: recognizes and binds cyclic di-GMP (c-di-GMP), a second messenger produced by bacteria, cyclic UMP-AMP (2',3'-cUAMP), and cyclic GMP-AMP (cGAMP), a messenger produced by CGAS in response to DNA virus in the cytosol. Upon binding to c-di-GMP, cUAMP or cGAMP, STING1 oligomerizes, translocates from the endoplasmic reticulum and is phosphorylated by TBK1 on the pLxIS motif, leading to recruitment and subsequent activation of the transcription factor IRF3 to induce expression of type I interferon and exert a potent anti-viral state. Exhibits 2',3' phosphodiester linkage-specific ligand recognition: can bind both 2'-3' linked cGAMP (2'-3'-cGAMP) and 3'-3' linked cGAMP but is preferentially activated by 2'-3' linked cGAMP. The preference for 2'-3'-cGAMP, compared to other linkage isomers is probably due to the ligand itself, which adopts an organized free-ligand conformation that resembles the STING1-bound conformation and pays low energy costs in changing into the active conformation. In addition to promote the production of type I interferons, plays a direct role in autophagy. Following cGAMP-binding, STING1 buds from the endoplasmic reticulum into COPII vesicles, which then form the endoplasmic reticulum-Golgi intermediate compartment (ERGIC). The ERGIC serves as the membrane source for WIPI2 recruitment and LC3 lipidation, leading to formation of autophagosomes that target cytosolic DNA or DNA viruses for degradation by the lysosome. Promotes autophagy by acting as a proton channel that directs proton efflux from the Golgi to facilitate MAP1LC3B/LC3B lipidation. The autophagy- and interferon-inducing activities can be uncoupled and autophagy induction is independent of TBK1 phosphorylation. Autophagy is also triggered upon infection by bacteria: following c-di-GMP-binding, which is produced by live Gram-positive bacteria, promotes reticulophagy (By similarity). May be involved in translocon function, the translocon possibly being able to influence the induction of type I interferons. May be involved in transduction of apoptotic signals via its association with the major histocompatibility complex class II (MHC-II) (By similarity). Involved in intercellular immune signaling. Cross-activated by 2',3'-cGAMP previously generated in virus-infected cells, triggers type I interferon signaling in macrophages and uninfected neighboring cells to propagate and amplify the antiviral immune response. (Microbial infection) Antiviral activity is antagonized by oncoproteins, such as papillomavirus (HPV) protein E7 and adenovirus early E1A protein. Such oncoproteins prevent the ability to sense cytosolic DNA.
Synonyms: hSTING; ERIS; hMITA; MITA; STING; TMEM173; FLJ38577; NET23; MPYS; SAVI; STING-beta
Tractability: Small molecule: a structure with a bound ligand is known; a high-quality ligand is known. Antibody: its Gene Ontology location is reachable by antibodies, with high confidence; UniProt places it where antibodies can reach, with medium confidence; UniProt predicts a signal peptide or a membrane-spanning region. PROTAC: UniProt records ubiquitination sites on it; ubiquitination databases record sites on it; a small molecule that binds it is known. Other modalities: a drug acting on it is in phase 2 or 3 trials.
Chemical probes: SN-011 (high quality)
Gene: Protein-coding gene on chromosome 5 (139,475,528 to 139,482,935, reverse strand). Ensembl gene ENSG00000184584.
Subcellular location: Endoplasmic reticulum membrane; Cytoplasm, perinuclear region; Endoplasmic reticulum-Golgi intermediate compartment membrane; Golgi apparatus membrane; Cytoplasmic vesicle, autophagosome membrane; Mitochondrion outer membrane; Cell membrane
Subcellular location (Human Protein Atlas): Cytosol; Basal body; Nucleoplasm; Primary cilium; Vesicles
Pathways (Reactome):
Immune System: IRF3-mediated induction of type I IFN; Neutrophil degranulation; Regulation of innate immune responses to cytosolic DNA; STAT6-mediated induction of chemokines; STING mediated induction of host immune responses
Disease: Dengue virus activates/modulates innate and adaptive immune responses; SARS-CoV-1 activates/modulates innate immune responses; SARS-CoV-2 activates/modulates innate and adaptive immune responses
Gene Ontology:
Molecular function: 2',3'-cyclic GMP-AMP binding; cholesterol binding; cyclic-di-GMP binding; identical protein binding; phosphatidylinositol-3,5-bisphosphate binding; protein binding; protein homodimerization activity; protein kinase binding; protein serine/threonine kinase binding; proton channel activity; RNA polymerase II-specific DNA-binding transcription factor binding; signaling adaptor activity; transcription coactivator activity; ubiquitin protein ligase binding
Biological process: activation of innate immune response; antibacterial innate immune response; antiviral innate immune response; autophagosome assembly; cellular response to exogenous dsRNA; cGAS/STING signaling pathway; cytoplasmic pattern recognition receptor signaling pathway; defense response to virus; innate immune response; negative regulation of TORC1 signaling; pattern recognition receptor signaling pathway; positive regulation of canonical NF-kappaB signal transduction; positive regulation of cytokine production; positive regulation of defense response to virus by host; positive regulation of interferon-beta production; positive regulation of lysosome organization; positive regulation of macroautophagy; positive regulation of transcription by RNA polymerase II; positive regulation of type I interferon production; positive regulation of type I interferon-mediated signaling pathway; protein complex oligomerization; protein localization to endoplasmic reticulum; autophagy; cellular senescence; lipid homeostasis; and 3 more
Cellular component: autophagosome; cytosol; endolysosome membrane; endoplasmic reticulum membrane; endoplasmic reticulum-Golgi intermediate compartment membrane; endosome; Golgi membrane; mitochondrial outer membrane; STING complex; trans-Golgi network membrane; cytoplasmic vesicle membrane; perinuclear region of cytoplasm; plasma membrane; secretory granule membrane; serine/threonine protein kinase complex; autophagosome membrane; cytoplasm; endoplasmic reticulum; Golgi apparatus; peroxisome
Genetic constraint (gnomAD): Loss-of-function variants: 17 observed, 30.15 expected, observed/expected ratio (o/e) 0.56, 90% interval 0.38 to 0.85. The upper end of that interval is the gene's LOEUF score, 0.85, which puts it in group 3 of 6, group 1 being the genes least tolerant of losing a copy. Missense variants: 366 observed, 498.3 expected, observed/expected ratio (o/e) 0.73, 90% interval 0.67 to 0.8. Synonymous variants: 200 observed, 218.86 expected, observed/expected ratio (o/e) 0.91, 90% interval 0.81 to 1.03.
Homologues: Orthologues: chimpanzee STING1 (99% identical), macaque STING1 (93% identical), pig STING1 (77% identical), dog STING1 (77% identical), guinea pig STING1 (75% identical), mouse Sting1 (69% identical), rat Sting1 (69% identical), rabbit STING1 (68% identical), tropical clawed frog sting1 (35% identical), zebrafish sting1 (34% identical), Drosophila melanogaster Sting (18% identical).
Diseases named in the same sentence as STING1 in open-access papers:
STING1 is named in the same sentence as 646 diseases in open-access papers, as found by Europe PMC text mining. Sharing a sentence is not in itself a finding about the gene and the disease. The quoted sentences say what the papers report.
viral infection (462 papers, 2010 to 2026). "The cGAS-STING (also known as STING1) pathway is a prominent innate immune pathway that has been widely explored in response to viral infection and mitochondrial damage." (PMID 39399905, 2024). "Although CGAS was originally found to be required for STING1 activation during viral infection, recent studies have also reported a CGAS-independent STING1 pathway in response to different stimuli, including viral infection." (PMID 35769880, 2022). "Stimulator of interferon response cGAMP interactor 1 (STING) is a key regulator in innate immunity, especially in the defense against viral infections." (PMID 40111902, 2025). "One reason is that the lipid product 4-hydroxynonenal (4-HNE) inhibits STING1 activation by the carbonylation of STING1 in mouse primary peritoneal macrophages, suggesting that GPX4 may act as a promoter of STING1-mediated immune response during virus infection." (PMID 34078874, 2021).
melanoma (272 papers, 2016 to 2026). A malignant, usually aggressive tumor composed of atypical, neoplastic melanocytes. "Both melanoma cell lines showed again a very comparable expression pattern of antiviral genes, with low expression of most genes, except for STING1, IFNAR1, IFNAR2, and IFIH1, which were moderately expressed." (PMID 40955425, 2025). "This rewiring causes rapid, diminishing responses (tachyphylaxis) to type-I interferon downstream of STING1; tumor cell-intrinsic STING1 inhibitors reduce CIN-driven metastasis in melanoma, breast, and colorectal cancers." (PMID 40463121, 2025). "Furthermore, our results suggest that inhibition cGAS activity and deletion of Cgas and Sting1 block mechanical force‐induced CCL2 production in melanoma VHPV metastasis, thereby attenuating splenic monocytes/macrophages infiltration in the liver." (PMID 39737867, 2025). "To investigate whether the effects of STING-TBK1-Zyxin signaling were relied on IRF3, we inoculated B16-F10 melanoma cells into WT, Sting1−/−, Irf3−/−, or Zyxin−/−;Irf3−/− mice." (PMID 39304793, 2024). "However, when looking at the melanoma and glioblastoma cell lines, the highly sensitive U87 cell line did not express STING1 or CGAS, which could explain its sensitivity." (PMID 40955425, 2025). "Both melanoma cell lines and the LN229 glioblastoma cell line expressed STING1, but did not express CGAS, which could again explain their sensitivity." (PMID 40955425, 2025).
autoimmune disease (234 papers, 2013 to 2026). A disorder resulting from loss of function or tissue destruction of an organ or multiple organs, arising from humoral or cellular immune responses of the individual to their own tissue constituents. "Insufficient or overactivation of the STING1 pathway is associated with various pathological conditions, such as tumorigenesis, infection, disseminated intravascular coagulation, autoimmune disease and tissue damage." (PMID 36639648, 2023). "A recent study revealed that CSNK1A1 inhibits autoimmune diseases by promoting the autophagic degradation of STING1." (PMID 41213929, 2025). "Specific mutations within the STING1 gene result in constitutive activation of the STING pathway, thereby driving chronic inflammatory responses and the development of autoimmune diseases, as exemplified by STING-associated vasculopathy with onset in infancy (SAVI)." (PMID 41153813, 2025). "Studies highlight the importance of the ER-ERGIC/Golgi axis in the control of STING1 activation, demonstrate a “tug-of-war” between the ER and the ERGIC/Golgi for STING1, and suggest therapeutic strategies for inflammatory and autoimmune diseases." (PMID 35371032, 2022).
breast carcinoma (215 papers, 2016 to 2026). "A recent study shows that Eribulin, an anti-cancer drug used to treat breast cancer and liposarcoma, triggers cancer cell death via the STING1-dependent signaling axis, indicating its role as a cell-death-promoting factor." (PMID 38283944, 2023). "Finally, the ability to respond to cGAMP as measured by Sting1 expression was similar between colorectal cancer and breast cancer, but both express less Sting1 than lung carcinoma cell lines." (PMID 39622844, 2024).
STING-associated vasculopathy with onset in infancy (149 papers, 2016 to 2026). "COPA syndrome demonstrates phenotypic overlap with STING-associated vasculopathy with onset in infancy (SAVI), the latter due to gain-of-function mutations in STING1." (PMID 41805977, 2026). "Mutations in the STING1 gene cause STING-associated vasculopathy with onset in infancy (SAVI), characterized by recurring fevers and skin lesions." (PMID 40507791, 2025). "STING-associated vasculopathy with onset in infancy (SAVI) represents an identified rare type I interferonopathy, triggered by gain-of-function mutations in the STING1 gene." (PMID 40698081, 2025). "Here, we examine the modulatory effects of HAQ, AQ alleles on STING-associated vasculopathy with onset in infancy (SAVI), an autosomal dominant, fatal inflammatory disease caused by gain-of-function human STING1 mutations." (PMID 39291958, 2024). "STING-associated vasculopathy with onset in infancy (SAVI), a severe type I interferonopathy due to gain of function mutations in STING1, can also present with joint involvement." (PMID 37510809, 2023). "STING-associated vasculopathy with onset in infancy (SAVI) is an autoinflammatory disease caused by mutations in the STING1 gene, resulting recurrent fevers, ulcerative skin lesions, vasculitis, and interstitial lung disease." (PMID 37354378, 2023). "Gain-of-function mutations in STING1 (human transmembrane protein 173 gene), which result in constitutive activation of STING, have been reported to cause an autoinflammatory syndrome termed SAVI (STING-associated vasculopathy with onset in infancy)." (PMID 37884945, 2023). "Gain-of-function variants in the stimulator of interferon response cGAMP interactor 1 (STING1) gene cause STING-Associated Vasculopathy with onset in Infancy (SAVI)." (PMID 36275728, 2022). "STING-associated vasculopathy with onset in infancy (SAVI) is a type I interferonopathy caused by gain-of-function mutations in STING1 encoding stimulator of interferon genes (STING) protein." (PMID 35159128, 2022). "In STING-associated vasculopathy with onset in infancy (SAVI), gain-of-function alleles of STING1 cause constitutive type I IFN responses." (PMID 36261523, 2022). "The earliest discovered cases of ligand-independent STING activation are gain-of-function (GOF) STING1 (also known as TMEM173) mutations in a rare autoinflammatory disease named STING-associated vasculopathy with onset in infancy (SAVI)." (PMID 35084490, 2022). "STING-associated vasculopathy with onset in infancy (SAVI) is an autosomal dominant disorder due to gain-of-function mutations in STING1, also known as TMEM173, encoding for STING." (PMID 33133092, 2020). "Heterozygous STING1 mutations cause another severer AiCL, STING-associated vasculopathy with onset in infancy (SAVI) showing interstitial lung disease and ulcerating skin lesions." (PMID 32256502, 2020). "In addition, clinical overlap was noted with the well-defined type I interferonopathy due to gain-of-function (GOF) mutations in STING1, termed STING-associated vasculopathy with onset in infancy (SAVI)." (PMID 41395910, 2025). "Gain-of-function mutations in STING1 (also known as TMEM173) which result in constitutive activation of STING, have been reported to cause STING-associated vasculopathy with onset in infancy (SAVI)." (PMID 37884945, 2023).
lung cancer (129 papers, 2019 to 2026). A malignant neoplasm involving the lung. "Although the elevated levels of 15‐PGDH and STING1 have not been previously associated with ALK alterations, both proteins have been implicated in other genetic mutations in lung cancer." (PMID 40621945, 2025).
Sepsis (113 papers, 2019 to 2026). Sepsis is defined as life-threatening organ dysfunction caused by a dysregulated host response to infection. "Recently, the activation of the STING1 pathway in myeloid cells, such as macrophages and monocytes, has been associated with inflammation, coagulation, and tissue damage in mouse models of sepsis." (PMID 38020710, 2023). "In summary, the activity of STING1 is regulated by various binding proteins or posttranslational modifications associated with immunity, autophagy, and cell death, highlighting the complex contribution of STING1 to the development of diseases, particularly sepsis and coagulation‐related conditions." (PMID 38020710, 2023). "We and others have recently demonstrated that excessive activation of the STING1 pathway contributes to cytokine storms, systemic coagulation, and multiple organ failure in experimental models of sepsis." (PMID 35769880, 2022). "Then we tested the impact of Sting1 depletion on sepsis at the single-cell level by conducting single-cell RNA sequencing (sc-seq) analysis of cells derived from wildtype (WT) and Sting1−/− intestinal tissue from sham or CLP mice." (PMID 35902564, 2022). "Excessive activation of STING1 pathway is involved in pathogenesis of sepsis and is recently reported to drive lethal coagulation in sepsis through GSDMD-dependent mechanism." (PMID 33796108, 2021). "STING1 mRNA expression in blood mononuclear cells is correlated with the severity of disseminated intravascular coagulation in patients with sepsis." (PMID 34199319, 2021). "Excessive activation of STING1 participates in the pathologic process of sepsis and initiates coagulation." (PMID 34199319, 2021). "To clarify whether STING is the trigger of ferroptotic injury in sepsis-induced organ damage, we evaluated the activation of STING-related proteins, ferroptosis-related indexes, and mortality in Sting1−/− and WT mice who suffered from CLP modeling." (PMID 35902564, 2022). "Moreover, mRNA expression of STING1 and GSDMD in peripheral blood mononuclear cell (PBMC) closely correlates with DIC severity in patients with sepsis, highlighting the regulatory role of STING1 in DIC during sepsis." (PMID 33796108, 2021). "To determine the significance of STING1-mediated ACOD1 expression in vivo, we used two mouse models, including one for endotoxemia as well as polymicrobial sepsis induced by cecum ligation and puncture (CLP)." (PMID 35769880, 2022). "In contrast, the interaction of notch intracellular signaling domain (NICD) with STING1 CBD limits STING1-mediated apoptosis in CD4+ T cells, preventing immunosuppression in the late stage of sepsis." (PMID 35371032, 2022). "Subsequent analysis of isolated peritoneal macrophages confirmed that STING1 is required for inducible ACOD1 expression and itaconate production in the setting of experimental endotoxemia or polymicrobial sepsis." (PMID 35769880, 2022). "Overall, these studies indicate that STING1-mediated itaconate production promotes, rather than inhibits, the development of sepsis." (PMID 35769880, 2022). "Consequently, the conditional deletion of STING1 in myeloid cells fails to produce ACOD1 and itaconate, thereby protecting mice against endotoxemia and polymicrobial sepsis." (PMID 35769880, 2022).
Autoimmunity (104 papers, 2015 to 2026). The occurrence of an immune reaction against the organism's own cells or tissues. "For example, STING-mediated autoimmunity occurs in humans with specific mutations in TREX1, STING1, and COPA, albeit with distinct molecular, immunological, and clinical phenotypes." (PMID 37247757, 2023).